NMRAL2P (NmrA like redox sensor 2, pseudogene)
Synonyms: LOC344887; formerly NMRAL1P1
Gene: Transcribed unprocessed pseudogene on chromosome 3 (185,960,039 to 185,979,837, forward strand). Ensembl gene ENSG00000171658.
Diseases named in the same sentence as NMRAL2P in open-access papers:
NMRAL2P is named in the same sentence as 7 diseases in open-access papers, as found by Europe PMC text mining. Sharing a sentence is not in itself a finding about the gene and the disease. The quoted sentences say what the papers report.
colon cancer (3 papers, 2019 to 2025). "Transcriptomic analysis in SFN‐exposed colon cancer cells revealed the non‐coding RNA Loc344887, regulated by Nrf2 and aiding NQO1 activity, identified as NMRAL2P." (PMID 40556338, 2025). "NMRAL2P, another pseudogene identified in SFN‐exposed colon cancer cells, is regulated by the Nrf2 pathway and enhances antioxidant activity and carcinogen detoxification." (PMID 40556338, 2025). "NmrA-like redox sensor 2 pseudogene (NMRAL2P) is the first functional pseudogene that was identified as a direct target of NRF2 and downstream regulator of NRF2-dependent NQO1 activation in sulforaphane (SFN)-treated colon cancer cells." (PMID 33287295, 2020).
heart failure (1 paper, 2023). Inability of the heart to pump blood at an adequate rate to meet tissue metabolic requirements. "Moreover, expression level of NMRA-like protein NMRAL1 pseudogene (NMRAL2P) is significantly decreased in the right ventricle in heart failure, suggesting that NMRAL2P is involved in heart failure." (PMID 37491351, 2023).
cancer (5 papers, 2017 to 2025). A tumor composed of atypical neoplastic, often pleomorphic cells that invade other tissues. "Although its precise function remains to be clarified, potential roles for NMRAL2P as a prognostic factor and/or a therapeutic target for cancer have been reported." (PMID 30737573, 2019). "Only NMRAL2P was substantially expressed in cancer tissues and predicted a poor prognosis." (PMID 37810778, 2023).
tumor (4 papers, 2019 to 2025). "Compared with the control group, the expression of NMRAL2P increased around 100x in the overexpression group, and compared to the vector, the NMRAL2P overexpression increased the viability, migration, invasion, and proliferation of tumor cells." (PMID 37810778, 2023). "NMRAL2P-oe was transferred into TU177 and AMC-HN-8 cells and the results showed that the overexpression of NMRAL2P enhanced the proliferation, migration, and invasion of tumor cells." (PMID 37810778, 2023). "MTS, Transwell, and clone formation assays showed that NMRAL2P overexpression increased the viability, migration, invasion and proliferation of tumor cells, while ENO1 gene knockout partially counteracted this tumor promoting effect." (PMID 37810778, 2023). "The cytoplasmic portion of NMRAL2P can bind to the ENO1 protein, postpone ENO1’s breakdown, promote glycolysis, and provide extra energy to tumor cells." (PMID 37810778, 2023). "Functional recovery assays were carried out to further clarify the role of NMRAL2P and ENO1 in tumor promotion." (PMID 37810778, 2023). "According to data retrieved from TCGA, NMRAL2P exhibits notably lower expression in human CRCs than in normal tissues, suggesting its potential as an emergent tumor suppressor biomarker." (PMID 40556338, 2025). "In the lncRNA group, lncRNA-TOB2P1, LOC100499489, lnc-NMRAL2p, and lnc-NBPF22P were markedly upregulated in tumor tissues, while LINC01093, LOC100130899, LOC200772, and lnc-FENDRR were significantly downregulated in tumor tissues, compared to the adjacent controls." (PMID 31156698, 2019). "In contrast, NMRAL2P and SHH showed significant negative correlations with multiple immune checkpoint genes, indicating that tumors with higher expression of these genes tend to display a “cold tumor” immune microenvironment, which may correspond to a poorer response to immunotherapy." (PMID 41425595, 2025).
head and neck tumors (2 papers, 2023 to 2025). "Only NMRAL2P was highly expressed in head and neck tumors and high expression of the gene was associated with poor prognosis." (PMID 37810778, 2023). "The lncRNA NMRAL2P is linked to oxidative stress regulation in head and neck tumors." (PMID 40556338, 2025). "To reverse-verify the function of NMRAL2P in head and neck tumor cells, we transferred NMRAL2P-ASO into TU177 and AMC-HN-8 cells, respectively, and the relative expression of NMRAL2P in TU177 and AMC-HN-8 was knocked down by more than 40%." (PMID 37810778, 2023). "The overexpression of NMRAL2P led to an increase in lactic acid synthesis, and the downregulation of ENO1 led to a decrease in lactic acid production, indicating that NMRAL2P acts on ENO1 to promote head and neck tumor cells." (PMID 37810778, 2023).
NMRAL2P also shares sentences with these, for which no sentence is quoted: gallbladder cancer (1 paper); lung adenocarcinoma (1).